SPATA31A6 (SPATA31 subfamily A member 6)
Description:
May play a role in spermatogenesis.
Synonyms: FAM75A6; OTTHUMG00000013224
Tractability: Antibody: UniProt predicts a signal peptide or a membrane-spanning region.
Gene: Protein-coding gene on chromosome 9 (42,183,659 to 42,189,887, forward strand). Ensembl gene ENSG00000185775.
Subcellular location: Membrane
Subcellular location (Human Protein Atlas): Acrosome; Equatorial segment
Gene Ontology:
Cellular component: membrane
Genetic constraint (gnomAD): Loss-of-function variants: 9 observed, 9.89 expected, observed/expected ratio (o/e) 0.91, 90% interval 0.55 to 1.57. That is too few expected variants to judge how well the gene tolerates losing a copy. Missense variants: 806 observed, 844.55 expected, observed/expected ratio (o/e) 0.95, 90% interval 0.9 to 1.01. Synonymous variants: 300 observed, 315.57 expected, observed/expected ratio (o/e) 0.95, 90% interval 0.86 to 1.05.
Homologues: Orthologues: mouse Spata31 (28% identical), rat Spata31 (28% identical). Paralogues in human: SPATA31A1 (98% identical), SPATA31A3 (98% identical), SPATA31A7 (98% identical), SPATA31A5 (98% identical), SPATA31C1 (76% identical), SPATA31C2 (73% identical), SPATA31E1 (34% identical), SPATA31D1 (27% identical), SPATA31D3 (18% identical), SPATA31D4 (18% identical), SPATA31F1 (17% identical), SPATA31F3 (2% identical).